TAOK2 (TAO kinase 2)
Description:
Serine/threonine-protein kinase involved in different processes such as membrane blebbing and apoptotic bodies formation DNA damage response and MAPK14/p38 MAPK stress-activated MAPK cascade. Phosphorylates itself, MBP, activated MAPK8, MAP2K3, MAP2K6 and tubulins. Activates the MAPK14/p38 MAPK signaling pathway through the specific activation and phosphorylation of the upstream MAP2K3 and MAP2K6 kinases. In response to DNA damage, involved in the G2/M transition DNA damage checkpoint by activating the p38/MAPK14 stress-activated MAPK cascade, probably by mediating phosphorylation of upstream MAP2K3 and MAP2K6 kinases. Isoform 1, but not isoform 2, plays a role in apoptotic morphological changes, including cell contraction, membrane blebbing and apoptotic bodies formation. This function, which requires the activation of MAPK8/JNK and nuclear localization of C-terminally truncated isoform 1, may be linked to the mitochondrial CASP9-associated death pathway. Isoform 1 binds to microtubules and affects their organization and stability independently of its kinase activity. Prevents MAP3K7-mediated activation of CHUK, and thus NF-kappa-B activation, but not that of MAPK8/JNK. May play a role in the osmotic stress-MAPK8 pathway. Isoform 2, but not isoform 1, is required for PCDH8 endocytosis. Following homophilic interactions between PCDH8 extracellular domains, isoform 2 phosphorylates and activates MAPK14/p38 MAPK which in turn phosphorylates isoform 2. This process leads to PCDH8 endocytosis and CDH2 cointernalization. Both isoforms are involved in MAPK14 phosphorylation.
Synonyms: hKFC-C; PSK-1; PSK1; KIAA0881; MAP3K17; PSK; TAO1; TAO2; PSK1-BETA; Tao2beta
Tractability: Small molecule: a high-quality ligand is known; it belongs to a druggable protein family. Antibody: UniProt predicts a signal peptide or a membrane-spanning region. PROTAC: it is named in the literature on targeted protein degradation; ubiquitination databases record sites on it; its protein half-life has been measured; a small molecule that binds it is known.
Target class: STE protein kinase STE20 family; Enzyme; Kinase; STE protein kinase group; STE protein kinase TAO subfamily; Protein Kinase
Chemical probes: TAO Kinase inhibitor 1 (high quality)
Gene: Protein-coding gene on chromosome 16 (29,973,868 to 29,992,261, forward strand). Ensembl gene ENSG00000149930.
Subcellular location: Cytoplasmic vesicle membrane; Cytoplasm, cytoskeleton; Nucleus; Cell projection, dendrite (Isoform 2)
Subcellular location (Human Protein Atlas): Cytosol; Nucleoplasm; Nucleoli
Gene Ontology:
Molecular function: mitogen-activated protein kinase kinase binding; neuropilin binding; protein binding; protein serine/threonine kinase activity; MAP kinase kinase kinase activity; protein serine/threonine kinase activator activity; tau protein binding; tau-protein kinase activity; ATP binding; protein kinase activity; protein serine kinase activity
Biological process: actin cytoskeleton organization; axonogenesis; DNA damage response; focal adhesion assembly; mitotic G2 DNA damage checkpoint signaling; positive regulation of JNK cascade; positive regulation of MAPK cascade; positive regulation of stress-activated MAPK cascade; regulation of cell shape; stress-activated MAPK cascade; apoptotic process; basal dendrite arborization; basal dendrite morphogenesis; cell migration; protein targeting to membrane; regulation of actin cytoskeleton organization; regulation of cell growth; cell morphogenesis involved in neuron differentiation; neuron projection morphogenesis
Cellular component: cytoplasmic vesicle; nucleolus; nucleoplasm; receptor complex; actin cytoskeleton; axon; axonal growth cone; cytoplasm; dendritic growth cone; neuron projection; cytoplasmic vesicle membrane; cytoskeleton; dendrite; nucleus
Genetic constraint (gnomAD): Loss-of-function variants: 43 observed, 120.71 expected, observed/expected ratio (o/e) 0.36, 90% interval 0.28 to 0.46. The upper end of that interval is the gene's LOEUF score, 0.46, which puts it in group 2 of 6, group 1 being the genes least tolerant of losing a copy. Missense variants: 1,264 observed, 1,637.8 expected, observed/expected ratio (o/e) 0.77, 90% interval 0.74 to 0.81. Synonymous variants: 704 observed, 680.64 expected, observed/expected ratio (o/e) 1.03, 90% interval 0.97 to 1.1.
Homologues: Orthologues: chimpanzee TAOK2 (99% identical), macaque TAOK2 (99% identical), dog TAOK2 (96% identical), pig TAOK2 (95% identical), guinea pig TAOK2 (94% identical), rat Taok2 (92% identical), rabbit TAOK2 (90% identical), mouse Taok2 (63% identical), tropical clawed frog taok2 (59% identical). Paralogues in human: TAOK1 (48% identical), TAOK3 (40% identical), SLK (19% identical), TNIK (18% identical), MAP4K4 (17% identical), STK10 (17% identical), MINK1 (16% identical), NRK (14% identical), MAP4K3 (14% identical), MAP4K5 (13% identical), MAP4K1 (13% identical), STK24 (13% identical), and 23 more.
Diseases named in the same sentence as TAOK2 in open-access papers:
TAOK2 is named in the same sentence as 41 diseases in open-access papers, as found by Europe PMC text mining. Sharing a sentence is not in itself a finding about the gene and the disease. The quoted sentences say what the papers report.
autism (11 papers, 2014 to 2025). Persistent deficits in social interaction and communication and interaction as well as a markedly restricted repertoire of activity and interest as well as repetitive patterns of behavior. "The kinase thousand and one amino acid kinase 2 (TAOK2) regulates dendritic architecture and synaptic plasticity and is implicated in neurodevelopmental and neuropsychiatric disorders, including autism and schizophrenia." (PMID 41210984, 2025). "Recently, patients with TAOK2 variants were reported to exhibit neurodevelopmental abnormalities, with 75% showing macrocephaly and autism phenotypes, further highlighting the clinical relevance of TAOK2 variants." (PMID 41210984, 2025). "Disease association analyses revealed significant enrichment of Taok2-regulated DEGs in gene sets linked to psychiatric disorders, particularly autism and schizophrenia." (PMID 41210984, 2025). "Deletion of Taok2 in mice was found to lead to deficits in dendritic growth, synaptic formation, cortical layering, and autism-associated phenotypes." (PMID 33339955, 2021). "TAOK2 is a MAP3K that is located in a region of chromosome 16p11.2 carrying susceptibility to autism." (PMID 25309320, 2014). "Multiple DEGs from both cortical layers are indeed associated with mental disorders, including autism, schizophrenia, bipolar disorder, Alzheimer’s disease, and neurodevelopmental disorders, confirming that TAOK2 is part of a network that is highly relevant to these neuropsychiatric disorders." (PMID 41210984, 2025). "Given that TAOK2 is a validated risk gene for autism, schizophrenia, and Alzheimer disease, pharmacological targeting of TAOK2 or its downstream pathways may offer a promising therapeutic avenue for these neurodevelopmental and neuropsychiatric disorders." (PMID 41210984, 2025). "Loss of TAOK2 activity causes autism-related neurodevelopmental and cognitive abnormality." (PMID 37400444, 2023). "Furthermore, Sept7 was found to be a phosphorylation target of thousand-and-one amino acid kinase 2 (TAOK2), a serine/threonine kinase encoded by the autism risk gene TAOK2." (PMID 35602601, 2022). "TAOK2 is an autism susceptibility gene encoding a serine/threonine kinase." (PMID 33642997, 2021). "For example, de novo copy number loss or missense variants in TAOK2, one of the kinase gene implicated by the enriched gene sets of the kinase activity and MAPK signaling, has been demonstrated to cause autism and other NDD." (PMID 30532227, 2018). "Interestingly, TAOK2 and MAPK3, are the only two genes in this locus that have been independently associated with autism." (PMID 33642997, 2021).
schizophrenia (11 papers, 2017 to 2025). A major psychotic disorder characterized by abnormalities in the perception or expression of reality. "Pleiotropy was supported by our cross-sectional GWAS enrichment analyses for EWAS, showing that TAOK2 overlapped with genomic loci previously linked to schizophrenia, as well as obsessive compulsive disorder and bipolar disorder." (PMID 36385171, 2023). "However, as the 16p11.2 copy number variation (CNV) duplication is associated with schizophrenia, this suggests that elevated expression of TAOK2 may also be detrimental to neuron development." (PMID 29467497, 2019). "With regards to genes with probes at suggestive significance at school-age (WDR20, MOV10, and TAOK2), these have previously been linked to neurodevelopmental and psychiatric risk, such as autism spectrum disorder (ASD) and schizophrenia." (PMID 36385171, 2023). "In the results of schizophrenia, known schizophrenia genes like WBP1L (p = 2.24E-14), TMTC1 (p = 3.75E-14), ZNF804A (p = 8.50E-14), TAOK2 (4.82E-12) and so on showed significant association." (PMID 35004692, 2021). "TAOK2 is located in the autism spectrum disorder (ASD) and schizophrenia-associated 16p11.2 chromosomal deletion region and is associated with other neurodevelopmental phenotypes." (PMID 29467497, 2019). "Previous studies did not denote any association between NRK and schizophrenia; however, an important paralog of this gene is TAOK2, which is essential for dendrite morphogenesis and has been associated with autism spectrum disorder." (PMID 28195569, 2017). "Furthermore, we identified six genes—GRK2, KLF3, TAOK2, ARFGAP45, AP1M1, and GPAT2—that were shared across gene sets associated with both brain function and clinical symptoms, suggesting a common transcriptional basis for these features of schizophrenia." (PMID 41271614, 2025). "A heterozygous deletion of the 16p11.2 locus, which contains 27 protein coding genes, including TAOK2, is linked to autism spectrum disorders, while a duplication of the same chromosomal region is associated with bipolar disorder, autism spectrum disorder (ASD), and schizophrenia." (PMID 41210984, 2025). "Therefore, either a reduction or elevation in TAOK2 gene dosage could be pathogenic, consistent with deletions or duplications of the 16p11.2 locus, which harbors TAOK2 and confers a risk for ASD and schizophrenia, respectively." (PMID 29467497, 2019). "An intersection analysis revealed six genes-GRK2, KLF3, TAOK2, ARFGAP45, AP1M1, and GPAT2-common to both brain function and clinical symptomatology gene sets, highlighting a shared genetic etiology in schizophrenia’s neuroimaging and clinical manifestations." (PMID 41271614, 2025). "This may be relevant for 16p11.2 deletion/duplication carriers who do not develop ASD/schizophrenia, but the Het deletion/duplication of TAOK2 may be sufficient for a NDD in these individuals." (PMID 29467497, 2019).
autism spectrum disorder (8 papers, 2014 to 2025). A spectrum of developmental disorders that includes autism, and Asperger syndrome. "Here, we show that Taok2, which is encoded in humans within the autism spectrum disorder (ASD) susceptibility locus 16p11.2, is essential for neuronal migration." (PMID 36123424, 2022). "TaoK2 has recently been shown to affect dendritic and synaptic development in mammals, and has been linked to Autism spectrum disorders (ASDs) based on patient mutations that alter its kinase activity." (PMID 31383864, 2019). "Although very little is known about the relationship of TAOKs to neurodegenerative diseases, the TAOK2 gene is located on chromosome 16p11.2, a region that carries significant susceptibility for autism spectrum disorders and schizophrenia." (PMID 29730992, 2018). "A recent study has also identified three missense mutations in TAOK2 in autism spectrum disorder subjects and shown that the expression of mutated forms of TAOK2 or increased expression of wild type TAOK2 impairs dendritic spine development in primary neurons." (PMID 29730992, 2018). "TAOK2 is a serine/threonine kinase associated with autism spectrum disorder." (PMID 40202048, 2025).
Anxiety (5 papers, 2019 to 2025). Intense feelings of nervousness, tension, or panic often arise in response to interpersonal stresses. "With regard to anxiety, Kctd13 and Taok2 loss of function in mice promoted anxiety‐like behaviors." (PMID 39988938, 2025). "Taken together, the increased thigmotaxis and increased peripheral locomotion, without affecting overall locomotor activity, suggest a highly specific effect of the Taok2 knockout on anxiety-related behavior." (PMID 41210984, 2025). "The cell-type-dependent inactivation of Taok2 in excitatory neurons thus appears sufficient to elicit a robust anxiety-like phenotype, as observed by the strong thigmotactic behavior." (PMID 41210984, 2025). "Taok2 cKO mice exhibited a strong and robust thigmotaxis phenotype in this test, a measure of anxiety." (PMID 41210984, 2025). "Previously, it was reported that constitutive homozygous Taok2 knockout mice showed behavioral abnormalities in cognition, anxiety, and social interaction." (PMID 41210984, 2025). "Recently, we found gene-dosage-dependent impairments in cognition, anxiety, and social interaction in Taok2 heterozygous (Het) and knockout (KO) mice, highlighting that a loss of Taok2 produces ASD-like phenotypes." (PMID 36123424, 2022). "We performed behavioral analysis on Taok2 heterozygous (Het) and knockout (KO) mice and found gene dosage-dependent impairments in cognition, anxiety, and social interaction." (PMID 29467497, 2019). "Taok2 knockout mice showed impairment in cognition, anxiety, and social interaction." (PMID 39988938, 2025). "However, the specific neuronal signaling pathways and cellular and regulatory mechanisms through which TAOK2 influences anxiety-related phenotypes remain incompletely understood." (PMID 41210984, 2025). "Taok2 cKO mice exhibited an anxiety-related thigmotactic behavior in the open field test." (PMID 41210984, 2025). "However, mice with a genetic deletion specifically of the Taok2 gene exhibit hyperactivity and reduced anxiety in a novel environment." (PMID 32704009, 2020). "Hence it seems likely that Taok2 gene haploinsufficiency contributes to these phenotypes observed in the current study, especially since reduced JNK signalling (the downstream target of TAOK2) also decreases anxiety and increases locomotion." (PMID 32704009, 2020). "In summary, all our findings support the notion that TAOK2 modulates calcium and ERK/MAPK signaling, which in turn influence neuronal activity, dendritic and synaptic architecture, and anxiety-related behaviors." (PMID 41210984, 2025). "In addition, fecal pellet number was slightly, albeit not significantly, higher for Taok2 cKO mice in the open field, further supporting an anxiety-like phenotype." (PMID 41210984, 2025).
viral infection (3 papers, 2020 to 2025). "We confirmed variants with putative driver role of MAP10, MPZL1, RPS6KA1, SETD1B, TAOK2, TMEM127, and TNFRSF1A genes, and of genes linked to viral infections (DDX3X and RSF1) and DNA repair (PAXIP1)." (PMID 32321919, 2020). "Interestingly, many of the candidate proteins have only limited functional links to viral infection and immune regulation and were not previously known to interact with NAs (e.g., c8orf88, DTYMK, KIF2A, PDAP1, PDIA5, TAOK1, TAOK2, and VRK1)." (PMID 34853303, 2021).
breast carcinoma (2 papers, 2017 to 2026). "The thousand and one (TAO) kinases, TAOK1, TAOK2, and TAOK3, have garnered great interest for their role in, and therapeutic potential for, breast cancer, neurodegeneration in human tauopathies, and a large number of neurodevelopmental disorders (NDDs)." (PMID 41530942, 2026). "Both TAOK2 and HCK are overexpressed in breast cancers, based on patient data provided by cBioPortal." (PMID 28771473, 2017). "We show relative expressions of TAOK2, HCK and STK10 in different breast cancer cell lines in S6 Fig." (PMID 28771473, 2017). "Two of these candidate kinases, TAOK2 and HCK, have not been previously investigated as regulators of EMT and acquisition of cell motility/invasion in breast cancer, although one group recently referenced TAOK2 as a potential activator of TNBC cell growth." (PMID 28771473, 2017).
colon cancer (2 papers, 2017 to 2020). "Here, we demonstrated that the predicted G4 sequence in the 5′ UTR of TAOK2 folds into a parallel quadruplex in vitro and a mutation in a patient with colon cancer increases the Tm value of the mutated TAOK2 RNA G4 oligo and decreases the translation efficiency compared to the wild-type." (PMID 28386116, 2017). "FuSiOn identified ten kinases (BMP2K, DCLK3, LIMK2, MAP2K5/MEK5, MAP3K3/MEKK3, ROS1, SIK2, TAOK2, ULK1, and ULK2) whose depletion mimicked the phenotypic effect of p62 depletion in HCT116 colon cancer cells." (PMID 33101709, 2020).
epilepsy (2 papers, 2013 to 2024). A brain disorder characterized by episodes of abnormally increased neuronal discharge resulting in transient episodes of sensory or motor neurological dysfunction, or psychic dysfunction. "Some of these variants are found in genes relevant to ASD and epilepsy, including RBFOX1, DLGAP2 and TAOK2." (PMID 38283851, 2024). "Nonetheless, given the high scores of both DOC2A and TAOK2, it is not unreasonable to hypothesize that one or more other genes in the region might also contribute to the epilepsy seen in these subjects." (PMID 24086149, 2013).
inflammatory bowel disease (2 papers, 2022). A spectrum of small and large bowel inflammatory diseases of unknown etiology. "Homozygous TAOK2 variant causes abnormal T cell activation in two patients with inflammatory bowel disease." (PMID 36250618, 2022).
melanoma (2 papers, 2024 to 2025). A malignant, usually aggressive tumor composed of atypical, neoplastic melanocytes. "In this study, LINC01198 is identified highly upregulated and acts as driving factor, which associates with TAOK1/TAOK2 to activate Hippo pathway and transcriptionally induce IL-1B expression for supporting melanoma resistance against vemurafenib." (PMID 41145465, 2025).
Obesity (2 papers, 2021 to 2023). Accumulation of substantial excess body fat. "Screening Hippo pathway genes in larger human cohorts revealed rare variants in TAOK2 associated with human obesity." (PMID 34748544, 2021). "Given the association between rare variants in TAOK2 and severe obesity, we assessed the functional significance of this finding by knockdown of tao expression in Drosophila." (PMID 34748544, 2021). "Interestingly, TAOK2 is located on human chromosome 16p11.2, a region in which deletions are associated with neurodevelopmental disorders and obesity." (PMID 34748544, 2021). "With this approach, we were not only able to identify 7 genes most likely to regulate human adiposity, we were also able to predict further novel candidate human obesity genes, for example, TAOK2, which we then showed to be functionally relevant as a regulator of obesity in Drosophila." (PMID 34748544, 2021). "To test these hypotheses in an independent cohort, we interrogated very rare variants (MAF < 0.025%) in TAOK2, DCHS1, and FAT4 in approximately 50,000 exomes from UK Biobank using a case–control approach for severe obesity (n = 925 cases, BMI > 40 kg/m2; n = 46,673 controls, BMI ≤ 40 kg/m2)." (PMID 34748544, 2021).
Alzheimer disease (1 paper, 2025). A progressive, neurodegenerative disease characterized by loss of function and death of nerve cells in several areas of the brain leading to loss of cognitive function such as memory and language. "TAOK2 is also associated with neurodegenerative disorders such as Alzheimer disease, as it phosphorylates tau protein, which forms pathogenic fibrils when hyperphosphorylated." (PMID 41210984, 2025).